TNF (tumor necrosis factor)
Diseases named in the same sentence as TNF in open-access papers (continued):
Sharing a sentence is not in itself a finding about the gene and the disease.
colitis (continued). "Cinacalcet also reduced production of the inflammatory cytokines TNFα, IL-1β, and IL-6 in the colon and sera of mice with DSS-induced colitis." (PMID 34880751, 2021). "In intrarectal administration of TNBS-induced colonic inflammation model, EA at ST36 decreased TNF-α, IL-6, and IL-1β levels in plasma and MPO activities in colonic tissues." (PMID 35095910, 2021). "blossom, and then further determine the effect of these flavonoids on lymphocyte proliferation; natural killer (NK) cell killing activity; TNF-α, IFN-γ, and IL-2 concentrations in serum; and the spleen lymphocyte apoptosis of colitis mice." (PMID 33562018, 2021). "All colitis-treated groups (HAC, HC, and AC) showed significantly higher gene expression of TNFα in comparison to the HA group, the colonized rats treated with antibiotics (p < 0.01 for all comparisons with HA)." (PMID 33499240, 2021). "It is reported that the tea extracts significantly decreased the production of proinflammatory cytokines (IL-6 and tumor necrosis factor-α (TNF-α))and increased the anti-inflammatory IL-10 in RAW264.7 macrophages and colitis mice." (PMID 34439208, 2021). "Another flavonoid, myricetin, downregulates inflammatory factors including TNF-α, IL-6, IL-1β, NF-κB, p-NF-κB, PCNA, COX-2, and cyclin D1 in AOM/DSS-induced colitis in mice." (PMID 34950252, 2021). "Ginsenoside Rg1 has been reported to inhibit the release of pro-inflammatory cytokines (IL-1β and TNF-α) by upregulating the expression of NLRP2 and then weaken the inflammatory response of DSS-induced colitis in mice." (PMID 33462754, 2021). "It was also found that TNF-α level measured 3 days after administration of TNBS was lower in group CβGl+, whereas 7 days after the induction of colitis, an increase in the TNF-α level was observed in the CβGh+ group." (PMID 33923129, 2021). "A murine model of colitis included SAM in a study of antioxidants as colitis treatment; SAM reduced serum amyloid A and TNF-α, improved reduced glutathione in circulation, and restored colonic length." (PMID 35052225, 2021). "In experimental colitis, disease severity is often positively correlated with the levels of MPO activity and pro-inflammatory cytokines, such as TNF-α and IL-1β." (PMID 33967768, 2021). "Curcumin with glucan particles efficiently reduced the TNF-α, IL-1β, and IL-6 activity as compared to the physical mixture of native curcumin and glucan particles in DSS-induced colitis in rats." (PMID 33918207, 2021). "Otherwise, when treating DSS-induced colitis mice with FCPS, it not only decreased the TLR4 expression but also down-regulated the manufacturing of pro-inflammatory cytokines including IL-1β, TNF-α, and IL-6." (PMID 34199820, 2021). "In a DSS-colitis C57BL/6 mouse model, sucralose treatment increased the expression of TNFα, TLR4, and Myd88 but decreased the expression of IL-10 and IκBα." (PMID 34631773, 2021). "Our laboratory has reported that ILK inhibition in a mouse model of colitis blocked NF-κB (IKK and p65) activation, and suppressed TNF-α, IL-6, and IL-1β production as well as infiltration of inflammatory cells." (PMID 34163519, 2021). "The promote relationships between TNF-α and Vascular Endothelial Growth Factor-C (VEGF-C), ARRB1 and VEGF-C has been confirmed in many diseases including pulmonary hypertension, colitis and gallbladder cancer 22-24." (PMID 33753990, 2021). "Several pro-inflammatory cytokines, e.g., TNFα, IL-1β, IL-6, and IL-17A, are known to be involved in DSS-induced colitis." (PMID 33871822, 2021). "Emerging experimental and clinical data have indicated that pro-inflammatory cytokines such as TNF-α, IFN-α and IL-6 play crucial roles in pathogenesis of colitis." (PMID 33461587, 2021). "In particular, results from previous study showed that apo-bLF was more efficient than the holo form in decreasing MPO, IL-1β, and TNF-α synthesis in trinitrobenzenesulfonic acid (TNBS)-induced colitis in rats and dextran sulfate (DSS)-induced colitis in mice." (PMID 34901112, 2021).
colitis (continued). "The expression levels of TNF-α and IL-6 were also increased in PBLDIEC−/− mice compared with WT mice with TNBS-induced colitis." (PMID 34059646, 2021). "To further examine the involvement of TNF in GP2 production, we administrated TNF-neutralizing or control antibodies to DSS-colitis mice during the colitis induction period." (PMID 33594081, 2021). "Our study found that TNF-a, IL-6, NO, MPO, and MPA levels increased in the colitis group and decreased after antioxidant therapy." (PMID 34912469, 2021). "In another study that used DSS-induced acute colitis model, both LF EA (LEA) and HF EA (HEA) decreased the level of IL-1β, TNF-α, IL-6, and IL-12 in serum." (PMID 35095910, 2021). "The present study confirmed and extended this effect by detecting a substantial reduction of IL-1α, IL-1β, IL-6, TNF-α, INF-γ, G-CSF, IL-13, GM-CSF, IL-3, MIP-1α, RANTES, and eotaxin cytokines in response to UTA77 treatment in both colitis models." (PMID 34497514, 2021). "Extracellular vesicles at 100 μg/mL from L. kefirgranum reduced the gene expression of IL-2, IL-8, and TNFα proinflammatory cytokines by 58, 64, and 67%, respectively, in Caco-2 cells for DSS-induced acute colitis model." (PMID 34745425, 2021). "IL-6 and TNF-α gene expression was upregulated in most intestinal inflammations such as IBD, colitis, and necrotizing enterocolitis." (PMID 34646877, 2021). "Ginsenoside Rh2 significantly decreased the expression of IL-6, TNF-α, and IFN-γ in mice with DSS-induced colitis." (PMID 33462754, 2021). "Compared with the DSS induced colitis mice model group, administration of Schisandrin B more significantly reduced the serum TNF-α, IL-6, IL-18 and IL-1β levels in DSS induced colitis mice model." (PMID 34628369, 2021). "In this study, we determined that arbutin considerably downregulated the levels of inflammatory cytokines (IL-1β, IL-6, and TNF-α) and proteins (iNOS and COX-2) in colitis mice." (PMID 34594215, 2021). "Using ELISA, we also found the expression levels of the pro-inflammatory cytokines TNF-α, IL-6, IFN-γ, and IL-1β were increased in PBLDIEC−/− mice versus WT mice with DSS-induced colitis." (PMID 34059646, 2021). "As well, decreased levels of IL-1β, IL-6, IL-8, and TNF-α in the plasma, and decreased levels of IL-6 and TNF-α, and increased level of MPO in the colon were shown in mice with colitis treated by EGCG-FMT compared with other three groups." (PMID 34493333, 2021). "Oral administration of boldine attenuates DSS-induced colitis and reduces colonic phosphorylation of STAT3 and NF-κB p65 subunit as well as the expression of TNFα, IL-6, and IL-17." (PMID 32855621, 2020). "In our data, pinocembrin remarkably suppressed the mRNA expression of TLR4, Myd88, iNOS, COX-2 and TNF-α, as well as the increased protein expression of TLR4 and phosphorylated NF-κB p65 in the colon of DSS colitis mice." (PMID 32687156, 2020). "In our study, the topical administration of SPG-antisense TNF-α suppressed TNF-α production by macrophages and significantly improved dextran sodium sulfate (DSS)-induced colitis." (PMID 31968666, 2020). "SSP and 5-ASA significantly reduced IL-1β, IL-4, IL-9, and IL-17A concentrations in the colitis mice, followed by lower expression of the CD11c+CD103+E-cadherin+ and CD11c+CD103+TNF-α+ cells." (PMID 32754049, 2020). "Exploration of the general inflammatory markers in colitis using western blot, showed that COX-2 and TNF-α expression in both colitis + 5-ASA and colitis + TOE groups was markedly diminished compared to that in the colitis group." (PMID 33092149, 2020). "We also observed that sinapic acid treatment significantly reduced the mRNA expression levels of TNF-α, IL-1β, IL-6, IL-8, IL-17α, and IFN-γ in the colons of colitis mice." (PMID 33312339, 2020). "TPC immunomodulates by stimulating colon anti-inflammatory cytokines (IL-10) and by downregulating pro-inflammatory cytokines (IL-1β, IL-17, and TNF-α) in collagen-induced arthritis model and DSS-induced colitis model." (PMID 32486445, 2020).
colitis (continued). "According to researchers, flavonoids suppressed the activation of TLR-4/NF-κB p65 signaling pathway, leading to a decrease in gene expression of TNF-α, IL-1B, and IL-6, COX-2, TFF-3, and iNOS proteins in the intestinal mucosa in colitis model." (PMID 32848723, 2020). "TMSCs administration alleviated the clinical severity of colitis, with further improvement in the order of IFN-γ and TNF-α priming prior to injection." (PMID 33276479, 2020). "For example, administration of ALA (450 mg/kg) in rats showed a beneficial effect on colonic iNOS expression and GSH concentration and inflammatory stress (reduced secretion of TNFα and mRNA level) induced by TNBS-colitis." (PMID 33603741, 2020). "In the present study, an SPG-antisense TNF-α complex was prepared, and its therapeutic efficacy was examined using a dextran sodium sulfate (DSS)-induced colitis model." (PMID 31968666, 2020). "In summary, synthetic pyridinols 14n, 14k, 14c, 14j, 13b, 18c, and 18d compounds showed strong inhibitory effects against TNF-α action in vitro and TNBS-induced colitis in vivo." (PMID 31619080, 2020). "The results indicated that SSP inhibited pro-inflammatory factors (as IL-6, IL-17A, IL-23, and TNF-α) and improved IL-10 expression, or restrained TGF-β1 in the colonic tissue of colitis mice." (PMID 32581849, 2020). "For instance, engineering anti–CTLA-4 to selectively localize its activity at the tumor site prevented peripheral toxicity and treatment with TNF inhibitors concomitantly with CTLA-4 and PD1 antibodies ameliorated colitis while improving antitumor efficacy." (PMID 32817121, 2020). "In contrast, vitamin D analog BXL-62 showed significant reduction in proinflammatory cytokine expression such as TNF-α, and induced CYP24A1 expression in peripheral blood mononuclear cells in DSS-induced colitis in mice." (PMID 32422882, 2020). "It has been noted that the reduction in inflammatory cytokines, such as TNF-α, IL-6, IL-1β, IFN-γ, and IL-17A, in the serum represents a target for IBD therapy, as they play leading roles in the formation of colitis." (PMID 32751784, 2020). "Although α7nAChR agonists reduced NF-κB transcriptional activity, IL-6 and TNF release, α7nAChR agonists worsened the effects of DSS-induced colitis or were ineffective in a model of TNBS-induced colitis." (PMID 32265899, 2020). "As far as we know, this is the first time to confirm the therapeutic effect by applying EVs derived from stem cells pretreated with inflammatory cytokines such as TNF-α and IFN-γ to colitis murine model." (PMID 32034203, 2020). "In our results, we demonstrated that repeated EA intervention ameliorates DSS-induced colitis by suppressing proinflammatory mediators, including CRP, IFN-γ, TNF-α, and IL-6 through the TLR4 signaling via MyD88-dependent pathway." (PMID 32419794, 2020). "These natural compounds significantly reduced the values of specific serum oxidative and proinflammatory markers (superoxide dismutase, myeloperoxidase, malondialdehyde, prostaglandin E2, TNF-α, IL-β, and C-reactive protein) in TNBS -induced colitis." (PMID 32867139, 2020). "A highly prevalent gut anaerobe, Faecalibacterium prausnitzii, and its culture supernatant decreased TNF-α and increased IL-10 secretion in mice with 2,4,6-trinitrobenzenesulphonic acid (TNBS)-induced colitis." (PMID 33281770, 2020). "Colon tissues from the naive, colitis, Exo, IFN-γ Exo, and miRNA treated mice were collected for the detection of TNF-α, IFN-γ, and IL-6." (PMID 32733020, 2020). "It is found that TMP (80 mg/kg) treatment attenuates the damage caused by intrarectal instillation of oxazolone (OXZ) and substantially reduces the rise in TNF-α and NF-κBp65 expressions, and increases PPAR-γ production in colitis mice." (PMID 32063999, 2020). "Intrarectal treatment of colitis with 30 mg/kg chitosan alone and with 30 mg/kg 5-ASA for 3 days led to a significant decrease in MPO, ALP, TNF-α, IL-6, IL-1β and NF-κB in colitis mice compared to untreated mice." (PMID 33138176, 2020).
colitis (continued). "Moreover, MSC-derived exosomes alleviate colitis in vivo by inhibiting expression of IL-7 and inducible nitric oxide synthase (iNOS) in mouse colonic macrophages, thus limiting the production of nitric oxide and the expression of TNF-α, IL-6 and IL-1β and increasing IL-10 secretion." (PMID 32365813, 2020). "Curcumin decreased the expression of Th1 cytokines (IL-12, IFN-γ, TNF-α) and increased that of Th2 cytokines (IL-4 and IL-10) in colon mucosa and thereby exerted therapeutic effects on TNBS-induced colitis." (PMID 32153570, 2020). "In an acute colitis mode, IV administration of a dose corresponding to 20 μg siRNA showed that TACE expression was inhibited, resulting in significant reductions of TNF-α (~75%), IL-1β (~75%) and IL-6 (~50%) production." (PMID 32545207, 2020). "Earlier studies demonstrated the detrimental effects of TNF-α in IBD and that the blockade of this cytokine was effective in ameliorating the severity of colitis in both the T cell transfer and the DSS mouse models." (PMID 33042131, 2020). "As the two classic inflammatory DCs promote colitis, we revealed that expression of CD11c+CD103+E-cadherin+ and CD11c+CD103+TNF-α+ cells was increased in mice with DSS-induced colitis." (PMID 32754049, 2020). "Cocoa phenolic compounds exhibited an anti-inflammatory effect decreasing the expression of TNF-α, IL-17, and STAT3 in colonic tissues during DSS colitis." (PMID 33299531, 2020). "gulates NLRP12, inhibits the release of IL-1β and TNF-α, and reduces DSS-induced inflammatory response in colitis in mice." (PMID 32547403, 2020). "In this study, the concomitant application of HnAb reduced the intestinal inflammatory damage induced by DSS, assessed by the colitis score, MPO expression and the expression levels of the cytokines IL-1β, IFN-γ, TNF-α in colonic tissues." (PMID 33193406, 2020). "Similar to the results in the colitis model, the ultralow dose of DPI significantly decreased the plasma levels of IL-6 and TNF-α compared with those in the control group." (PMID 32550901, 2020). "Studies consistently reported results showing that vitamin D supplementation can downregulate inflammatory pathways of COX-2, TNF-α, NF-κB, and MAPK, modify cell kinetics, and alter gut microbiome, all of which contribute to an improved state of colitis." (PMID 32422882, 2020). "Dietary resveratrol treatment ameliorates the increases of secretions of TNF-α and IL-1β and phosphorylation of p65 in DSS-induced colitis mice." (PMID 33664740, 2020). "The level of inflammation cytokines TNF-α, IFN-γ, and IL-6 of the colon tissue and lipocalin-2 (LCN2) of feces and serum were significantly elevated in colitis mice." (PMID 32733020, 2020). "The inhibition of adenosine deaminase was reported to attenuate mucosal inflammation in experimental colitis through the mechanism of reducing the production of MDA and TNF-α levels." (PMID 32074166, 2020). "In the current study, it was observed that the acute colitis model increased the level of TNF-α, while vitamin D application decreased the level of TNF-α." (PMID 32555936, 2020). "In the present study, it was observed that the levels of CRP, IFN-γ, TNF-α, and IL-6 were elevated in mice plasma with DSS-induced colitis." (PMID 32419794, 2020). "Consistent with the results of a previous experiment, increased levels of the cytokines IL1α, TNF‐α, IL6, IL12P40 and MIP‐1A were observed in mice with DSS‐induced colitis." (PMID 32363766, 2020). "One study in Smad3-/- colitis-prone mice found that in dietary DHA enhanced LPS-induced B-cell secretion of IL-6 and TNFα, and also increased CD40 expression versus controls." (PMID 33603741, 2020). "BM-MSC exosomes reduced tissue damage, limited myeloperoxidase activity in colon, decreased IL-1β, TNFα and iNOS levels in the tissue in a rat model of 2,4,6-trinitrobenzene sulphonic acid (TNBS)-induced colitis." (PMID 32595362, 2020).
colitis (continued). "In the present study, increased production of iNOS, COX-2, IL-6, TNF-α, and IL-1β was observed in mice with DSS-induced colitis." (PMID 33536931, 2020). "First, we found that the colonic mRNA expression levels of the proinflammatory mediators IL-1β, IFN-γ, IL-17A, and TNF-α, which had been confirmed to be involved in IBD, were upregulated notably in colitis mice compared to levels in normal controls." (PMID 32855978, 2020). "In accordance, increased amounts of colonic TNF-α and lipocalin-2 in FFD mice further demonstrated the protective effect of dietary cellulose on DSS-induced colitis." (PMID 33079623, 2020). "The dramatically elevated mRNA expression levels of MCP-1, TNF-α, IL-6, IL-1β, and IFN-γ in the colon are important features of the DSS colitis model." (PMID 33042117, 2020). "At the same time, IL-6, IL-17A, IL-23, TNF-α, and TGF-β1 expressions were significantly decreased in colitis mice treated by SSP." (PMID 32581849, 2020). "Another polyphenol, Ellagic acid, shows similar effects by reducing the expression and production of IL-6 and TNF-α, and MAPK phosphorylation in colitis mice." (PMID 33664740, 2020). "The elevated level of inflammation cytokines IL-6, TNF-α, IFN-γ in colon, and LCN2 in feces and serum of colitis mice were decreased by miR-125a and miR-125b agomir injection." (PMID 32733020, 2020). "It has been shown that the levels of TNF-α, IL6, and IL1β were significantly increased in mice with colitis induced by saline in in vivo studies." (PMID 32265719, 2020). "In the DSS-induced acute colitis model, GPR4 antagonist 13 (NE-52-QQ57) ameliorates intestinal inflammation and decreases the expression of TNF-α in the inflamed mouse colon tissues." (PMID 33553219, 2020). "In two colitis models, 5 mg/kg intracolonic administered Gal–LMWC–ASO significantly reduced colonic TNF-α mRNA and protein levels." (PMID 32545207, 2020). "Further research has shown that thalidomide can reduce the levels of TNF-α, IL-1, IL-6, MPO, and NO in TNBS-induced mouse colitis, in turn reducing the inflammatory response in CD." (PMID 32766176, 2020). "In a mouse model of colitis, CUR treatment decreased the expression of TNF-α, IL-2, IL-6, IL-12 p40, IL-17, and IL-21 to a level comparable to healthy mice." (PMID 32423101, 2020). "In this study, we found that the serum levels of TNF-α, IL-1β, IL-6, IL-8, IL-17α, and IFN-γ in colitis mice were significantly decreased by treatment with sinapic acid." (PMID 33312339, 2020). "In contrast, sinapic acid was shown to reduce the generation and mRNA expression levels of some inflammatory cytokines (TNF-α, IL-1β, IL-6, IL-8, IL-17α, and IFN-γ) and reduce the activation of the NLRP3 inflammasome in the colons of colitis mice." (PMID 33312339, 2020). "Indole acrylic acid, a Trp metabolite produced by Peptostreptococcus spp., inhibits secretion of the pro-inflamatory cytokines IL1β, IL6, and tumor necrosis factor (TNF) in human peripheral blood mononuclear cells and ameliorates colitis in a mouse model." (PMID 33086747, 2020). "The proinflammatory cytokines, TNF-α and IFN-γ, can synergistically drive epithelial barrier dysfunction and apoptosis, particularly during colitis." (PMID 32934961, 2020). "In the current study, we found that alpinetin decreased the activation of NF-κB, the expression of pro-inflammatory mediator genes, the activity of MPO, and the production of TNF-α and IL-6 in DSS colitis mice." (PMID 32372959, 2020). "Chrysin is also capable of diminishing inflammatory markers such as MPO activity, TNF-α levels and NF-κB activation and translocation to the nucleus if administered previously to DSS-induced colitis mice." (PMID 32377161, 2020). "The mRNA levels of IL-1β, TNF-α, iNOS, IL-6, and iNOS were markedly increased in mice with DSS-induced colitis." (PMID 33536931, 2020).